SHBG (sex hormone binding globulin)
Diseases named in the same sentence as SHBG in open-access papers (continued):
Sharing a sentence is not in itself a finding about the gene and the disease.
metabolic syndrome (continued). "PCOS: Polycystic ovary syndrome; MetS: Metabolic syndrome; TT: Total testosterone; FAI: Free androgen index; SHBG: Sex hormone binding globulinData presented as Mean ± SD. *P-value refers to the independent samples t test; **P-value refers to the Mann-Whitney's U procedure." (PMID 32494764, 2020). "Sex hormone-binding globulin (SHBG) has been reported as a protein which could bind to testosterone and regulate its clinical action, and there is increasing evidence showing that lower circulating levels of SHBG contribute to T2DM and metabolic syndrome in the general population." (PMID 29707577, 2018). "For instance, our study included the Hyper Insulin, Bilirubin, SHBG-LpA, and ALP Negative clusters, whereas the T2DGGI study included clusters labeled as Body fat, Metabolic syndrome, and Residual glycemic." (PMID 37886436, 2023).
polycystic ovary syndrome (128 papers, 2009 to 2026). A disorder that manifests as multiple cysts on the ovaries. "In contrast, in women, low SHBG increases bioavailable androgens, potentially causing hirsutism, menstrual irregularities, and features of polycystic ovary syndrome." (PMID 41281936, 2025). "In current clinical practice, serum SHBG is generally considered to have significant diagnostic value in polycystic ovary syndrome, while in other situations, SHBG measurement is rarely performed." (PMID 38796576, 2024). "The majority of the patients with polycystic ovary syndrome were found to have deficient or suboptimal serum vitamin D levels, and the effects of vitamin D on the SHBG levels and free-androgen indices in these patients was examined." (PMID 37447279, 2023). "A previous study reported that a lower SHBG level is associated with several diseases, including liver disease, arthritis, polycystic ovarian syndrome, cancer, and cardiovascular disease." (PMID 34717706, 2021). "The predisposal to hyperandrogenemia can all be affected by both mutations in androgen receiver, sex hormone-binding globulin (SHBG), and steroidogenic enzymes genes." (PMID 34745009, 2021). "A recent Mendelian randomization study has suggested a causal role for sex hormone‐binding globulin (SHBG), total testosterone and free testosterone in the pathogenesis of polycystic ovary syndrome (PCOS)." (PMID 34277990, 2021). "SHBG encodes the sex hormone binding protein (SHBG), and variation at this locus has been related to polycystic ovary syndrome." (PMID 28842730, 2017). "Reduced SHBG levels may have significant clinical consequences and are commonly associated with obesity, insulin resistance, metabolic syndrome, and polycystic ovary syndrome." (PMID 41281936, 2025). "Android adipose tissue distribution may also be associated with hyperandrogenemia and decreased concentration of sex hormone binding globulin (SHBG)." (PMID 36235688, 2022). "Sex hormone‐binding globulin (SHBG), total testosterone, and free testosterone have been found to play a causal role in the pathogenesis of polycystic ovary syndrome (PCOS), but it remains uncertain how these androgen markers associate with individual features of PCOS." (PMID 34277990, 2021). "Hyperandrogenemia and low SHBG in early and middle age associates with AGM independently of BMI." (PMID 34153097, 2021). "Statins also lower dehydroepiandrosterone (DHEA) and sex hormone-binding globulin (SHBG), influencing the hormonal environment and potentially reducing cancer risk, particularly in women with polycystic ovary syndrome (PCOS)." (PMID 41011280, 2025). "Therefore, relatively lower serum SHBG levels have been established as a risk factor for adolescent polycystic ovary syndrome, aligning with our study results, where higher serum levels of SHBG had a protective effect on PCOS, assisting in predicting the occurrence of PCOS." (PMID 38779450, 2024). "Insulin has another mechanism which leads to hyperandrogenemia, i.e., inhibiting SHBG production in the liver." (PMID 40281834, 2025). "This would further exacerbate the impacts of insulin on ovarian steroidogenesis, hepatic SHBG production and androgen metabolism in peripheral tissues, thereby fueling the hyperandrogenemia-induced arrest of follicle development and oligo/anovulation." (PMID 40013621, 2025). "High insulin levels can inhibit serum SHBG levels, raising the concentration of free bioactive testosterone, ultimately leading to hyperandrogenemia." (PMID 40008316, 2025). "In the metabolic subtype, hyperandrogenemia results from low SHBG and in the reproductive subtype primarily from elevated testosterone." (PMID 41180187, 2025). "Previous observational studies have indicated an inverse correlation between circulating sex hormone binding globulin (SHBG) levels and the incidence of polycystic ovary syndrome (PCOS)." (PMID 38902677, 2024).
polycystic ovary syndrome (continued). "Hyperinsulinaemia (HI) can inhibit the expression of SHBG in the liver, thus aggravating hyperandrogenemia." (PMID 38374053, 2024). "Regarding hormonal balance, increases in SHBG levels and decreases in total testosterone were recorded, suggesting a reduction in the hyperandrogenemia typical of PCOS." (PMID 39599701, 2024). "Insulin resistance, hyperinsulinemia, type 2 diabetes, and polycystic ovarian syndrome (PCOS) are known to promote endometrial proliferation by reducing the levels of sex hormone binding globulin and insulin-like growth factor 1 (IGF-1) binding proteins." (PMID 39336931, 2024). "An animal experiment has shown that acetate can attenuate androgen excess and increase sex hormone binding globulin (SHBG) in polycystic ovary syndrome (PCOS)." (PMID 39519507, 2024). "Hyperandrogenemia is brought on by the decrease in SHBG, which raises the amount of free circulating testosterone in the blood." (PMID 37985173, 2023). "In patients with polycystic ovary syndrome, the sex hormone-binding globulin (SHBG) level is very low and the production of the male hormone testosterone is more." (PMID 35924049, 2022). "Under the condition of low SHBG, if TT is used as the evaluation index, hyperandrogenemia will be underestimated." (PMID 33583431, 2021). "Circulating SHBG is also correlated with endocrinology diseases such as polycystic ovary syndrome (PCOS) and hypothyroidism." (PMID 34335746, 2021). "Lower total and free E2 in oral contraceptive users are also seen in women with polycystic ovary syndrome in whom oral contraceptive are used to reduce free androgens by increasing SHBG levels and inhibiting ovarian steroid synthesis." (PMID 31720688, 2020). "Insulin indirectly exacerbates hyperandrogenemia by reducing hepatic biosynthesis of sex hormone binding globulin and increasing the free and bioavailable testosterone levels." (PMID 29670770, 2018). "It has been reported that vaspin levels are negatively correlated with serum follicle-stimulating hormone levels, sex hormone-binding globulin levels and positively correlated with free androgen index in women with polycystic ovary syndrome." (PMID 27604490, 2017). "Treatment with the PPARÎ3 agonist rosiglitazone has been shown to increase the blood levels of SHBG, especially in patients with polycystic ovarian syndrome." (PMID 24714992, 2014). "So, this study was performed to investigate the effect of omega-3 on sex hormone binding protein (SHBG), testosterone, free androgen index and menstrual status in women with polycystic ovary syndrome." (PMID 24639805, 2013). "Slightly elevated levels may be seen in women with polycystic ovary syndrome or those currently taking contraception due to a corresponding increase in sex hormone binding globulin (SHBG), but it’s rare in men." (PMID 41179064, 2025). "It not only effectively predicts decreased SHBG and elevated FAI—serving as an auxiliary tool for assessing hyperandrogenemia—but also shows an association with ovulatory dysfunction, although its specific applications require further validation in combination with other biomarkers." (PMID 41427050, 2025). "Furthermore, suppressed levels of SHBG may also act as a useful clinical biomarker for IR (including for other IR-associated conditions such as polycystic ovary syndrome [PCOS] and more generally such as the young male population)." (PMID 37367914, 2023). "Their findings showed that oxidative stress inhibits the expression and secretion of SHBG in laboratory conditions and may be an important factor in increasing the incidence of hyperandrogenemia in PCOS20." (PMID 36991023, 2023). "However, decreased SHBG levels increase the bioavailability of testosterone, which consequently increases hyperandrogenemia." (PMID 37062827, 2023).
polycystic ovary syndrome (continued). "We assume that in a pathological condition such as PCOS, numerous hyperandrogenemia-inducing mechanisms (e.g., IR, hypo-SHBG-emia, under-reported roles of systemic and ovarian renin-aldosterone-renin system) simply “overtrump” the impact of diet-related factors." (PMID 35010948, 2021). "Decreased SHBG levels increase the bioavailability of androgens, which in turn leads to progression of ovarian pathology, anovulation and the phenotypic characteristics of polycystic ovarian syndrome (PCOS)." (PMID 33139661, 2020). "For improving hyperandrogenemia, outcomes included TT, FT, SHBG, and AND." (PMID 32490533, 2020). "Manifestations of hyperandrogenemia are often related to low levels of SHBG." (PMID 33139661, 2020). "In a clinical study into the therapeutic effect of Glab on 32 women suffering from polycystic ovary syndrome, the administration of Glab (10 μM) ameliorated the syndrome by diminishing the serum testosterone and elevating the sex hormone-binding globulin level." (PMID 31592119, 2019). "It has been shown to reduce hyperandrogenemia by increasing the levels of SHBG." (PMID 26351529, 2015). "Notoriously, mutations in the genes of the androgen receptor, sex hormone binding globulin (SHBG), and steroidogenic enzymes may be especially important in predisposing to the development of hyperandrogenemia." (PMID 25763405, 2014). "Patients with polycystic ovary syndrome and hyperandrogenemia showed a BMI and SHBG independent correlation between chemokine levels and testosterone, further supporting that high testosterone levels may increase inflammation markers." (PMID 24089589, 2013). "SHBG in special populations: The impact of altered SHBG levels is particularly evident in specific populations, such as adolescents with polycystic ovary syndrome (PCOS) and individuals with glycogen storage disease type 1a (GSD1a)." (PMID 40625923, 2025). "This study aims to establish diagnostic cut-off values for Polycystic Ovary Syndrome (PCOS) and differentiate it from anovulatory dysfunction in adolescents, while evaluating the diagnostic sensitivity of the Free Androgen Index (FAI) and Sex Hormone Binding Globulin (SHBG)." (PMID 40861046, 2025). "Multiple studies have been performed in women with polycystic ovary syndrome (PCOS) in whom SHBG levels are low." (PMID 40863113, 2025). "However, the literature has so far not reported an association between AMH and SHBG in women with regular menstrual cycles, without elevated androgen levels, and without polycystic ovaries." (PMID 38541016, 2024). "Most often, the androgen used to assess hyperandrogenemia is free testosterone (fT), although total testosterone (TT), sex hormone binding globulin (SHBG), the free androgen index (FAI), dehydroepiandrosterone (DHEA), DHEA sulfate (DHEA-S), and androstenedione (A4) may also be altered." (PMID 33467251, 2020). "Indexes of hyperandrogenemia, including T, LH, LH/FSH, SHBG, and FAI improved in the CPA/EE+ Met group while only LH improved in the GLP-1RA+Met group." (PMID 37653215, 2024). "CPA/EE + Met was more effective in improving hyperandrogenemia, including T(total testosterone), LH, LH/FSH(Luteinizing hormone/follicle-stimulating hormone), SHBG(sex hormone-binding globulin) and FAI (free androgen index)." (PMID 37653215, 2024). "MET plus LIRA therapy improved hyperandrogenemia, including TT (total testosterone), SHBG (sex hormone binding globulin) and FAI (free androgen index), whereas MET monotherapy only improved SHBG and FAI when compared with baseline." (PMID 36060969, 2022). "First, as recent Mendelian randomization studies have shown that SHBG is causal in the pathogenesis of polycystic ovary syndrome (PCOS), the low serum SHBG levels may contribute to the higher prevalence of PCOS that has been observed in GSD1a." (PMID 35132570, 2022).
polycystic ovary syndrome (continued). "It exhibits strong binding affinity with testosterone and can regulate the activity of testosterone and other steroid hormones, assisting in their transportation into target tissues.In adults, researches has found a correlation between SHBG and the occurrence of NAFLD and polycystic ovary syndrome." (PMID 39980852, 2025). "Furthermore, although FAI is recommended for clinical use in the diagnosis of polycystic ovary syndrome (PCOS), it is a derived measure of testosterone that lacks certified reference ranges and may reflect changes in SHBG as well as testosterone." (PMID 37886900, 2024). "The significance of polycystic ovarian morphology and its relation to polycystic ovary syndrome (PCOS) is unclear, but probably it is associated with higher androgen and insulin levels and lower sex hormone binding globulin (SHBG) in absence of identifiable differences in gonadotropin dynamics." (PMID 19480717, 2009). "In the PIOMET group, FAI decreased significantly at the beginning of 4 weeks, and TT, SHBG, and FAI levels significantly improved with the extension of treatment time, suggesting that PIO and MET may play a synergistic role in reducing hyperandrogenemia in normal-weight women with PCOS." (PMID 38374053, 2024). "Additionally, vitamin D's influence on granulosa cell development may also occur by elevating the levels of sex hormone-binding globulin (SHBG), thereby improving the hyperandrogenic manifestations in patients with polycystic ovary syndrome (PCOS), further affecting granulosa cell proliferation." (PMID 40116548, 2025). "However, the relationship between serum SHBG concentrations and the ovarian response during controlled ovarian hyperstimulation (COH) and whether this relationship differs between women with and without polycystic ovary syndrome (PCOS) remains unclear." (PMID 34805198, 2021).
Hirsutism (90 papers, 2010 to 2026). Abnormally increased hair growth referring to a male pattern of body hair (androgenic hair). "The present study confirms the correlation between NAFLD and metabolic parameters in a cohort of patients with oligomenorrhea and/or hirsutism and identify a cut-off of SHBG able to predict the risk of NAFLD in this population." (PMID 33854482, 2021). "In our study, we found that oral isotretinoin caused hirsutism and menstrual irregularity and changes in fT, tT, and SHBG levels at the third and sixth month of treatment." (PMID 34548957, 2021). "Low levels of SHBG are associated with higher levels of free androgens that can manifest with hirsutism, acne, or irregular menstruations in PCOS patients." (PMID 34458674, 2021). "Table IV shows the association between acne, hirsutism, androgen hormone levels, and SHBG, depression and anxiety together with a total score of cognition and its domains." (PMID 33426415, 2020). "Moreover, chronic vitamin D deficiency may exacerbate low SHBG levels, thereby increasing the free androgen index and aggravating clinical symptoms such as hirsutism, acne, and menstrual irregularity." (PMID 40868057, 2025). "Hence, although isotretinoin decreases sebum expression owing to its anti-androgenic effects, it may cause a decrease in SHBG levels and an increase in the amount of free androgens, thus leading to hirsutism and menstrual irregularity." (PMID 34548957, 2021). "This therapeutic approach increases levels of sex hormone-binding globulin (SHBG), which in turn lowers free testosterone concentration and mitigates hirsutism." (PMID 40514618, 2025). "Bariatric surgery reduced menstrual irregularities, hirsutism, total and free testosterone, and antimullerian hormone, and increased SHBG." (PMID 41561041, 2025). "It has also been shown to reduce testosterone and the free androgen index (FAI) while increasing sex hormone-binding globulin (SHBG), improving symptoms like hirsutism and acne." (PMID 40869469, 2025). "The hormonal profile of PCOS typically includes elevated LH:FSH ratios, increased androgens (especially testosterone) and reduced sex hormone-binding globulin (SHBG), contributing to clinical manifestations such as hirsutism and ovulatory dysfunction." (PMID 40566517, 2025). "Sex hormone-binding globulin (SHBG) levels and the Ferriman–Gallwey hirsutism scores also showed beneficial changes." (PMID 40219003, 2025). "Supplementation with synbiotics had a beneficial effect on hirsutism scores and supplementation with synbiotics and probiotics significantly increased SHBG synthesis." (PMID 39940263, 2025). "Decreases in testosterone, increases in SHBG, and improvements in symptoms like hirsutism and menstrual irregularities were also observed." (PMID 39599701, 2024). "Although possible improvements in the modified Ferriman–Gallwey hirsutism score, levels of sex hormone-binding globulin, and free androgen index were identified and the results were not statistically significant." (PMID 38994457, 2024). "Compared with the placebo and after vitamin D treatment, the FAI index showed a decrease, sex hormone binding globulin (SHBG) levels showed improvement in three studies, and the modified Ferriman–Gallwey hirsutism (mF-G) score showed improvement." (PMID 38994457, 2024). "As demonstrated by the studies above, probiotics can decrease the production of androgens by increasing the levels of SHBG that bind and regulate free testosterone, subsequently improving hirsutism symptoms." (PMID 37375637, 2023). "Metabolic surgery contributed to marked improvement of abnormal menstruation, hirsutism, and levels of free testosterone, total testosterone, SHBG, and AMH in patients with PCOS." (PMID 35360056, 2022). "Treatment with oral contraceptives regulates menstrual cycle and increases SHBG levels, leading to decreased levels of free testosterone and decreased hirsutism scores." (PMID 35740476, 2022).